AGXT (alanine--glyoxylate aminotransferase)
Diseases named in the same sentence as AGXT in open-access papers (continued):
Sharing a sentence is not in itself a finding about the gene and the disease.
Hyperoxaluria (12 papers, 2014 to 2026). Increased excretion of oxalates in the urine. "This disease has three types, the most common being Type I, due to mutations in the AGXT gene which codes for alanine glyoxylate aminotransferase enzyme (AGT) that yield hyperoxaluria." (PMID 40428338, 2025). "Among these, 23 patients exhibited hyperoxaluria greater than 1.0 mmol/1.73 m2/24 h, and they were screened for mutations in the AGXT gene." (PMID 40791808, 2025). "Hyperoxaluria-related mutations were detected in nine patients (three AGXT defects, three GRHPR defects, and three HOGA1 defects), and calcium oxalate stones were found in eight of these patients as a result of stone sample evaluation." (PMID 37144129, 2023). "Both hyperoxaluric and non-hyperoxaluric patients were screened for sequence variations in known and candidate genes implicated in hyperoxaluria (AGXT, GRHPR, HOGA1, SLC26A1, SLC26A6, SLC26A7) by targeted next generation sequencing (tNGS)." (PMID 37270618, 2023). "Detection of the same genetic variant in HPRT1 and AGXT gene in two fetuses as observed in index cases with Lesch nehan syndrome and hyperoxaluria respectively helped in appropriate counselling and termination of pregnancy." (PMID 37464296, 2023). "The exome analysis revealed that other disease-causing mutations related to hyperoxaluria were also present in AGXT (PH1), and HOGA1 (PH3)." (PMID 36619171, 2022). "The enzyme defect is due to mutations in the AGXT gene on chromosome 2, leading to hyperoxaluria." (PMID 39464227, 2024). "To evaluate the contribution of genetic factors in the development of hyperoxaluria after bariatric surgery, we conducted tNGS to detect variations within genes known to cause monogenic hyperoxaluria and Ca-Ox-NL (AGXT, GRHPR, HOGA1; SLC26A1) as well as the candidate genes SLC26A6 and SLC26A7." (PMID 37270618, 2023). "In this study, Agxt-/- mice lacking exons 3-8 were characterized, confirming the complete loss of hepatic alanine-glyoxylate aminotransferase (AGT) expression and the presence of early-onset hyperoxaluria." (PMID 41972717, 2026). "PH1 is the most prevalent and severe form of hyperoxaluria, characterized by massive urinary oxalate excretion and severe renal impairment caused by a deficiency of alanine-glyoxylate aminotransferase (AGT) owing to mutations in the AGXT gene." (PMID 40225159, 2023). "Moreover, three genes, AGXT, HOGA1 and GRHPR with Novel variants known to cause hyperoxaluria were found frequently in the study cohort." (PMID 36619171, 2022).
kidney stones (9 papers, 2016 to 2025). "The hepatic peroxisomal enzyme alanine glyoxylate aminotransferase (AGT) defects encoded by the AGXT gene increase oxalate production, resulting in nephrocalcinosis, nephrolithiasis, chronic kidney disease, and kidney failure." (PMID 36704142, 2022). "Two novel AGXT missense mutations, and distinct morphology and inner-structure difference of kidney stones were found in this kindred, meanwhile, the possible underlying pathogenic mechanisms at molecular and clinical levels were described." (PMID 27644547, 2016). "The loss of function of the AGXT-encoded liver enzyme alanine:glyoxylate aminotransferase causes the liver to produce an excessive amount of oxalate, which accumulates in the kidney and induces kidney stones and kidney failure, leading ultimately to multi-organ damage." (PMID 35213992, 2022). "In the nephrolithiasis panel, AGXT should instead be considered the primary core gene candidate." (PMID 35456490, 2022).
kidney failure (5 papers, 2011 to 2025). An acute or chronic condition that is characterized by the inability of the kidneys to adequately filter the blood. "Here, we describe a patient with a frameshift variant, c.823_824dup, in the AGXT gene of PH1 who presented with renal failure recurrence after kidney transplantation, arteriovenous fistula (AVF) occlusion and subcutaneous calcification in adulthood." (PMID 40432890, 2025). "Apart from the c.508G>A (p.Gly170Arg) AGXT variant, which imparts a relatively favorable outcome, little is known about determinants of kidney failure." (PMID 37849991, 2023). "Primary hyperoxaluria type-1 (PH1) is a rare inherited autosomal recessive disorder in which a deficiency of the hepatic enzyme alanine-glyoxylate aminotransferase leads to endogenous oxalate overproduction, renal failure, systemic oxalate deposition and death." (PMID 25013605, 2011). "Including those outcomes would have given more information on the course of the disease in patients with different AGXT genotypes, whereas we now focus on the absence or presence of kidney failure at last follow-up." (PMID 37849991, 2023). "In this study, we report a patient with a frameshift variant, c.823_824dup, in the alanine-glyoxylate aminotransferase (AGXT) gene of PH1 who presented with renal failure recurrence after kidney transplantation, arteriovenous fistula (AVF) occlusion and subcutaneous calcification in adulthood." (PMID 40432890, 2025).
atherosclerosis (4 papers, 2023 to 2024). A disease characterized by the build-up of fatty material and calcium deposition in the arterial wall resulting in partial or complete occlusion of the arterial lumen. "Similarly, hepatic oxalate overproduction due to the loss of AGXT enhances atherosclerosis, while overexpression of AGXT in hepatocytes lowers oxalate and ameliorates atherosclerosis in Apoe−/− mice." (PMID 39333384, 2024). "Mice with knockout genes for alanine-glyoxylate aminotransferase (AGXT) showed decreased glycine/oxalate ratio and increased atherosclerosis, a striking effect confirmed in human patients." (PMID 39123599, 2024). "Though circulating AGXT has not been previously reported as a biomarker of diet or metabolic disease, impaired expression of the AGXT gene may contribute to the development of atherosclerosis, and AGXT in liver tissue may be a biomarker for hepatocellular carcinoma." (PMID 38337712, 2024).
hepatocellular carcinoma (3 papers, 2020 to 2024). A malignant tumor that arises from hepatocytes. "On the other hand, loss of alanine-glyoxylate aminotransferase (AGXT) expression has been reported to accelerate the progression of hepatocellular carcinoma." (PMID 33335484, 2020). "The top constituent gene, AGXT, is highly involved in colorectal cancer and hepatocellular carcinoma." (PMID 36980673, 2023).
liver cancer (2 papers, 2019 to 2022). An epithelial or non-epithelial malignant neoplasm that arises from the liver. "Therefore, more research should be conducted to fully investigate the detailed mechanism of AGXT in liver cancer progression, which can link amino acid metabolism with LCSCs and liver cancer malignancy." (PMID 35625596, 2022). "Unlike the unstable changes of the other four genes, the expression of AGXT was constantly reduced in tumors compared to nontumor tissues in a variety of malignant, including liver cancer, gastric cancer, kidney cancer, lung cancer and pancreatic cancer." (PMID 31771612, 2019).
urolithiasis (2 papers, 2014 to 2022). Stone(s) within the urinary tract. "Two unrelated patients with recurrent urolithiasis, along with members of their families, exhibited mutations in the AGXT gene by PCR direct sequencing." (PMID 24934730, 2014).
Calcium oxalate nephrolithiasis (1 paper, 2025). The presence of calcium- and oxalate-containing calculi (stones) in the kidneys. "AGXT catalyzes the conversion of glyoxylate to glycine, diverting it from oxalate synthesis—a process critical for preventing calcium oxalate nephrolithiasis in humans." (PMID 41150091, 2025).
fibrosis (1 paper, 2024). the formation of excess fibrous connective tissue in an organ or tissue in a reparative or reactive process. "As these transcriptional alterations suggest a reduction in hepatic fibrosis in response to lowering oxalate via AGXT overexpression, we next evaluated hepatic fibrosis through histopathological and immunofluorescence analyses coupled with biochemical verification." (PMID 39333384, 2024).
gout (1 paper, 2025). A condition characterized by painful swelling of the joints, which is caused by deposition of urate crystals. "The present study reveals a GAstV–bile acid–AGXT axis as a pivotal mechanism underlying viral gout, expanding our understanding of how RNA viruses subvert host metabolic networks to drive pathology." (PMID 41150091, 2025). "Moreover, we identify the upregulation of AGXT as a critical mechanism underlying GAstV-induced gout pathogenesis." (PMID 41150091, 2025). "Our findings pinpoint AGXT—a gene encoding alanine–glyoxylate aminotransferase—as a critical mediator of GAstV-associated metabolic dysregulation, offering novel insights into the intersection of viral infection and gout pathophysiology." (PMID 41150091, 2025). "Our findings propose that GAstV-induced activation of bile acid metabolism, particularly AGXT upregulation, drives hyperuricemia and subsequent gout pathology." (PMID 41150091, 2025). "This work unveils a novel metabolic mechanism for GAstV-induced gout, nominating AGXT as a promising target for breeding resistant poultry." (PMID 41150091, 2025). "Since the AGXT enzyme influences uric acid production, its virus-induced overexpression is a likely driver of hyperuricemia and gout." (PMID 41150091, 2025). "Our study provides the first transcriptomic evidence linking GAstV-induced renal injury to bile acid metabolic disruption, with AGXT—a key enzyme in glyoxylate detoxification—emerging as a central mediator of hyperuricemia and gout pathogenesis." (PMID 41150091, 2025). "AGXT upregulation may be one of the key mechanisms of GAstV-induced gout." (PMID 41150091, 2025). "However, whether AGXT plays a role in astrovirus-induced gout remains unknown." (PMID 41150091, 2025).
Hepatic steatosis (1 paper, 2024). Steatosis is a term used to denote lipid accumulation within hepatocytes. "The expression of AGXT significantly and inversely correlated with the severity of hepatic steatosis in our cohort of liver transplantation donors." (PMID 39333384, 2024). "Taken together, these findings indicate that lowering oxalate overproduction in MASH via AGXT overexpression attenuates hepatic steatosis through induction of FAO." (PMID 39333384, 2024).
hyperuricemia (1 paper, 2025). An abnormally high level of uric acid. "Paradoxically, GAstV-driven AGXT overexpression coincided with hyperuricemia, challenging the conventional view of AGXT as solely protective." (PMID 41150091, 2025).
Obesity (1 paper, 2024). Accumulation of substantial excess body fat. "Previous studies also reported that AGXT transcript is downregulated in livers from patients and mice with obesity, MASLD or MASH12,15–17." (PMID 39333384, 2024).
optic neuropathies (1 paper, 2024). "In addition to these patients with possible inherited optic neuropathies, six other patients (20.0% of patients with an alteration of the GCC) carried suspected unique pathogenic variants in six recessive genes (DPYD, AGXT, CYP1B1, ACO2, LTBP2 and FDXR)." (PMID 38796496, 2024). "The susceptibility variants identified in the other six patients were not firmly responsible on their own for a genetic form of optic neuropathy since they were found in recessives genes (DPYD, ACO2, AGXT, CYP1B1, LTBP2 and FDXR) with a single affected allele." (PMID 38796496, 2024).
renal tubular disease (1 paper, 2021). "For all patients, AGXT gene mutation was confirmed by second-generation sequencing and Sanger first-generation sequencing of target exons related to renal tubular disease." (PMID 33721035, 2021).
tumor (12 papers, 2019 to 2025). "The expression of AGXT in HCC was significantly associated to tumor differentiation (P < 0.0001)." (PMID 31771612, 2019). "However, it must be considered that AGXT may act as a tumor suppressor in HCC cells, and targeting it may also cause adverse effects." (PMID 35625596, 2022). "The tumor suppressor effect of AGXT in HCC seems to contradict the findings of this study that AGXT promotes stemness in LCSCs." (PMID 35625596, 2022). "AGXT knockdown in the spheroid cells significantly reduced the xenograft growth rate and tumor-forming ability in vivo." (PMID 35625596, 2022). "These in vivo data strongly support the critical role of AGXT in augmenting the tumor formation and growth rates of LCSCs." (PMID 35625596, 2022). "We provided a high level of evidence on AGXT to serve as a new biomarker and prognostic factor that related to tumor differentiation and progression for HCC." (PMID 31771612, 2019). "However, AGXT silencing in the Huh7 spheroid cells significantly reduced the tumor formation rate from 100% to 50% after the inoculation of 106 cells." (PMID 35625596, 2022). "Furthermore, we determined the effect of AGXT on tumor migration, colony formation in soft agar, and drug resistance." (PMID 35625596, 2022). "In the Huh7 spheroid cells, AGXT knockdown markedly reduced the tumor growth rate." (PMID 35625596, 2022). "Knocking down of AGXT in HCC cell line could induce a cell cycle shift from G0/G1 to S and G2/M together with enhanced cell proliferation, increased cell death and migration, suggesting a role of AGXT in promoting tumor progression." (PMID 31771612, 2019). "In the IHC analysis of tumor tissue from the affected member of this family, we observed a lack of expression of AGXT in tumor tissue, which could be indicating a loss-of-function (LOF) of the protein." (PMID 37175550, 2023). "In tumor samples taken from the GSE45001 and GSE32879 datasets, seven genes (APOA2, CAT, ACOX1, APOE4, AGXT, EHHADH, and HSD17B4) showed a substantial downregulation." (PMID 38274331, 2024). "Immunohistochemistry (IHC) staining for BTBD16, EpCAM, FOXM1, AGXT and JMJD1C was carried out in normal and tumor thyroid tissue samples (three patient biopsies available), belonging to two NMTC families: NMTC_1 and NMTC_4." (PMID 37175550, 2023). "We identified three genes (AGXT, PTGER3 and SLC12A3) with lower mRNA levels in tumour samples, and patients with a high expression of these three genes exhibited prolonged survival." (PMID 32144299, 2020). "Consistently, we found that ALOX5 was upregulated in the tumour samples, while AGXT, PTGER3, and SLC12A3 were downregulated in the tumour samples." (PMID 32144299, 2020). "The comparatively lower expression of AGXT, PTGER3 and SLC12A3 in tumours correlates with worse prognosis in KIRC patients, while higher expression of ALOX5 predicts reduced survival." (PMID 32144299, 2020). "However, in the GSE32879 dataset, only seven genes (APOA2, CAT, ACOX1, APOE4, AGXT, EHHADH, HSD17B4) were observed to be significantly reduced in tumor samples." (PMID 38274331, 2024). "The data implied that AGXT does not drive HCC stemness but is crucial for maintaining the tumor-initiating and self-renewal properties of LCSCs." (PMID 35625596, 2022). "On the other hand, previous studies reported that a high expression of AGXT can improve the prognosis of HCC patients, which indicates that AGXT may have other functions, such as promoting tumor immunity or other unfavorable factors to inhibit cancer progress." (PMID 35625596, 2022). "For instance, using WGCNA and a protein-protein interaction network, a recent study analyzed the gene expression pattern of 26 pairs of tumor tissues/adjacent tissues and identified four hub genes involved in the progression of KIRC, including AGXT, PTGER3, SLC12A3, and ALOX5." (PMID 33110456, 2020). "However, AGXT knockdown in the parental Huh7 cells did not significantly affect the tumor growth rate." (PMID 35625596, 2022).
tumor (continued). "The IHC staining of AGXT in nontumor liver tissues was strongly positive and was characterized by a granular, diffuse, cytoplasmic staining pattern; while in tumor tissues, the staining of AGXT on malignant hepatocytes were focal and/or pale in a majority of cases." (PMID 31771612, 2019). "The role of AGXT in tumor biology has not been reported yet." (PMID 31771612, 2019). "However, these apparently contradictory observations can be reconciled, in that AGXT may exert different tumor-regulatory roles in LCSCs and non-LCSCs." (PMID 35625596, 2022). "We finally obtained a list of only five genes (AGXT; ALDOB; CYP2E1; IGFBP3; TOP2A) that were differentially expressed in tumor and nontumor tissues across studies and were significantly correlated to HCC prognosis." (PMID 31771612, 2019). "The IHC observation reaffirmed that AGXT was highly expressed in nontumor liver tissues and was down-regulated in HCC tumor tissues (P < 0.0001)." (PMID 31771612, 2019).
cancer (4 papers, 2019 to 2024). A tumor composed of atypical neoplastic, often pleomorphic cells that invade other tissues. "The HLM score was constructed based on six genes, AGXT, TRIB2, ELFN2, PCDHB10, CALCA, and CD79A, which have been previously reported to be associated with the tumorigenesis and progression of various cancer types, including CRC, as well as chemotherapy resistance." (PMID 38902737, 2024). "Because AGXT expression cannot drive cancer stemness, we speculated that AGXT is involved in the maintenance of LCSCs." (PMID 35625596, 2022). "Considering that the AGXT gene is related to amino acid metabolism, it may be involved in the metabolic reprogramming of cancer cells to affect prognosis." (PMID 35625596, 2022). "On the basis of these data, we speculate that the metabolic effects of AGXT differ between differentiated cancer cells and CSCs." (PMID 35625596, 2022). "Our study demonstrated that AGXT, which is known to participate in amino acid metabolism, cannot directly promote HCC stemness, but is an essential gene to sustain the cancer stemness properties of LCSCs." (PMID 35625596, 2022). "Further well-designed and larger sample studies are surely warranted to identify the role of the AGXT in the development and progression of HCC and other malignant tumors." (PMID 31771612, 2019). "The knockdown of AGXT in LCSCs reduced the number of spheroids and the population of LCSCs; this implies that AGXT is required for the maintenance of cancer stemness rather than as a driver of LCSCs." (PMID 35625596, 2022). "Taken together, these data suggest that AGXT does not directly increase the capacity of cancer stemness to promote HCC malignancy." (PMID 35625596, 2022). "Their finding reaffirmed that AGXT as a new HCC biomarker, and backed up the feasibility and necessity of systematic review on discovering new and reliable biomarkers for HCC as well as for other cancer." (PMID 31771612, 2019). "Furthermore, the biological effects of AGXT-induced SOX2 and OCT4 between parental live cancer cells and LCSCs may be different." (PMID 35625596, 2022). "Furthermore, AGXT may upregulate the stemness transcription factors SOX2 and OCT4 to maintain cancer stemness in LCSCs." (PMID 35625596, 2022). "Mechanistically, AGXT may sustain the self-renewal potential of LCSCs by upregulating the expression of SRY-box transcription factor 2 (SOX2) and octamer-binding transcription factor 4 (OCT4), two well-known master regulators of cancer stemness." (PMID 35625596, 2022).
infection (3 papers, 2018 to 2025). The state of being infected such as from the introduction of a foreign agent such as serum, vaccine, antigenic substance or organism. "An alanine-glyoxylate aminotransferase (contig number 955) showed differential race specific expression during the first week of infection between "M" and "T" races." (PMID 29879135, 2018).
autosomal recessive disease (2 papers, 2014 to 2020). Autosomal recessive form of disease. "PH1 is a severe autosomal recessive inherited disorder of glyoxylate metabolism caused by mutations in the AGXT gene on chromosome 2q37.3 that encodes the liver-specific PLP-dependent enzyme AGT." (PMID 24934730, 2014). "This mutation may help to extend the spectrum of known AGXT mutations especially in our population since the incidence and prevalence of autosomal recessive diseases are expectedly high." (PMID 32569165, 2020).